RILPL1 (Rab interacting lysosomal protein like 1)
Description:
Plays a role in the regulation of cell shape and polarity (By similarity). Plays a role in cellular protein transport, including protein transport away from primary cilia (By similarity). Neuroprotective protein, which acts by sequestring GAPDH in the cytosol and prevent the apoptotic function of GAPDH in the nucleus (By similarity). Competes with SIAH1 for binding GAPDH (By similarity). Does not regulate lysosomal morphology and distribution. Binds to RAB10 following LRRK2-mediated RAB10 phosphorylation which leads to inhibition of ciliogenesis.
Synonyms: RLP1; FLJ39378; GOSPEL; OPDM4
Tractability: Antibody: its Gene Ontology location is reachable by antibodies, with high confidence. PROTAC: ubiquitination databases record sites on it.
Gene: Protein-coding gene on chromosome 12 (123,470,054 to 123,534,103, reverse strand). Ensembl gene ENSG00000188026.
Subcellular location: Cytoplasm, cytosol; Cytoplasm, cytoskeleton, microtubule organizing center, centrosome, centriole; Cytoplasm, cytoskeleton, cilium basal body
Subcellular location (Human Protein Atlas): Cytosol; Plasma membrane; Primary cilium; Basal body; Centrosome; Nucleoplasm
Gene Ontology:
Molecular function: protein binding; dynein light intermediate chain binding; small GTPase binding; protein dimerization activity
Biological process: cilium assembly; epithelial cell morphogenesis; positive regulation of neuron apoptotic process; protein transport from ciliary membrane to plasma membrane
Cellular component: centrosome; ciliary basal body; cytosol; cilium; cytoplasm; centriole; membrane
Genetic constraint (gnomAD): Loss-of-function variants: 30 observed, 42.92 expected, observed/expected ratio (o/e) 0.7, 90% interval 0.52 to 0.95. The upper end of that interval is the gene's LOEUF score, 0.95, which puts it in group 4 of 6, group 1 being the genes least tolerant of losing a copy. Missense variants: 414 observed, 486.33 expected, observed/expected ratio (o/e) 0.85, 90% interval 0.79 to 0.92. Synonymous variants: 205 observed, 202.62 expected, observed/expected ratio (o/e) 1.01, 90% interval 0.9 to 1.14.
Homologues: Orthologues: chimpanzee RILPL1 (99% identical), dog RILPL1 (97% identical), pig RILPL1 (97% identical), rat Rilpl1 (94% identical), mouse Rilpl1 (94% identical), rabbit RILPL1 (93% identical), macaque RILPL1 (89% identical), tropical clawed frog rilpl1 (78% identical), guinea pig Rilpl1 (44% identical), Drosophila melanogaster Rilpl (30% identical), Caenorhabditis elegans rilp-1 (26% identical). Paralogues in human: RILP (25% identical), RILPL2 (19% identical), DZIP1 (18% identical), DZIP1L (18% identical).
Diseases named in the same sentence as RILPL1 in open-access papers:
RILPL1 is named in the same sentence as 10 diseases in open-access papers, as found by Europe PMC text mining. Sharing a sentence is not in itself a finding about the gene and the disease. The quoted sentences say what the papers report.
oculopharyngodistal myopathy (7 papers, 2022 to 2025). Oculopharyngodistal myopathy (OPDM) is a rare, adult-onset hereditary muscle disease. "Thereafter, CGG repeat expansions in GIPC1 and CCG repeat expansions in RILPL1 are also found to cause oculopharyngodistal myopathies." (PMID 36670296, 2023). "The expansion of several other CGG repeats located in 5’ UTRs have been implicated in oculopharyngodistal myopathy (OPDM): NOTCH2NLC, GIPC1, LRP12, RILPL1, and ABCD3." (PMID 39868092, 2025). "Oculopharyngodistal myopathy (OPDM) is a group of disorders caused by mutations in several genes such as LRP12, GIPC1, NOTCH2NLC and RILPL1." (PMID 39501809, 2024).
Parkinson disease (2 papers, 2022 to 2023). A progressive degenerative disorder of the central nervous system characterized by loss of dopamine producing neurons in the substantia nigra and the presence of Lewy bodies in the substantia nigra and locus coeruleus. "The Parkinson's-disease-associated LRRK2 kinase phosphorylates multiple Rab GTPases including Rab8 and Rab10, which enhances their binding to RILPL1 and RILPL2." (PMID 35776681, 2022).
ciliopathy (1 paper, 2022). A genetic disorder of the cellular cilia or the cilia anchoring structures, the basal bodies, or of ciliary function. "Lastly, our meta-analyses also found marginal evidence for an association between severe COVID-19 and pLoFs (M1) in RILPL1 (OR: 20.2, 95% CI: 5.8–70.7, p = 2.42x10-6), a gene that, like MARK1, is associated with microtubule formation and ciliopathy." (PMID 36327219, 2022).
epilepsy (1 paper, 2023). A brain disorder characterized by episodes of abnormally increased neuronal discharge resulting in transient episodes of sensory or motor neurological dysfunction, or psychic dysfunction. "RILPL1 was reported to be associated with several neurological diseases, such as epilepsy and familial temporal lobe dementia, while not any description with OPMD." (PMID 37864208, 2023).
RILPL1 also shares sentences with these, for which no sentence is quoted: amyotrophic lateral sclerosis (1 paper); Cognitive impairment (1); COVID-19 (1); distal myopathy (1); neurological diseases (1); tumor (1).